RTKN (rhotekin)
Description:
Mediates Rho signaling to activate NF-kappa-B and may confer increased resistance to apoptosis to cells in gastric tumorigenesis. May play a novel role in the organization of septin structures.
Synonyms: B5; RTKN-1
Tractability: PROTAC: ubiquitination databases record sites on it; its protein half-life has been measured.
Gene: Protein-coding gene on chromosome 2 (74,425,835 to 74,442,422, reverse strand). Ensembl gene ENSG00000114993.
Subcellular location (Human Protein Atlas): Mitochondria; Nucleoplasm
Pathways (Reactome):
Signal Transduction: RHO GTPases Activate Rhotekin and Rhophilins; RHOA GTPase cycle; RHOB GTPase cycle; RHOC GTPase cycle
Gene Ontology:
Molecular function: GTPase inhibitor activity; protein binding; small GTPase binding
Biological process: regulation of apoptotic process; Rho protein signal transduction; signal transduction; actomyosin contractile ring assembly; mitotic cytokinesis; septin ring organization
Cellular component: actomyosin contractile ring; cytosol
Genetic constraint (gnomAD): Loss-of-function variants: 49 observed, 66.07 expected, observed/expected ratio (o/e) 0.74, 90% interval 0.59 to 0.94. The upper end of that interval is the gene's LOEUF score, 0.94, which puts it in group 3 of 6, group 1 being the genes least tolerant of losing a copy. Missense variants: 685 observed, 769.72 expected, observed/expected ratio (o/e) 0.89, 90% interval 0.83 to 0.95. Synonymous variants: 295 observed, 303.02 expected, observed/expected ratio (o/e) 0.97, 90% interval 0.88 to 1.07.
Homologues: Orthologues: chimpanzee RTKN (99% identical), dog RTKN (93% identical), pig RTKN (92% identical), guinea pig RTKN (92% identical), mouse Rtkn (87% identical), rabbit RTKN (86% identical), macaque RTKN (86% identical), rat Rtkn (83% identical), zebrafish rtkna (55% identical), tropical clawed frog rtkn (44% identical). Paralogues in human: RTKN2 (38% identical), ANLN (18% identical).
Diseases named in the same sentence as RTKN in open-access papers:
RTKN is named in the same sentence as 20 diseases in open-access papers, as found by Europe PMC text mining. Sharing a sentence is not in itself a finding about the gene and the disease. The quoted sentences say what the papers report.
gastric cancer (8 papers, 2009 to 2026). A primary or metastatic malignant neoplasm involving the stomach. "Studies have reported that RTKN plays a role in promoting tumor progression in gastric cancer and HCC." (PMID 41535254, 2026). "For example, in gastric cancer, RTKN promotes NF-κB activation, thereby inhibiting tumor cell apoptosis and facilitating tumor progression." (PMID 41535254, 2026). "Studies indicate that the alcoholic extract of Zuo Jin Wan can downregulate RTKN expression, reduce glucose uptake, decrease extracellular lactate content in gastric cancer cells, and inhibit cell proliferation." (PMID 39906672, 2024). "The cell cycle-related protein Rho effector molecule Rhotekin (RTKN) is often found highly expressed in gastric cancer tissues." (PMID 39906672, 2024). "This suggests that a low expression of RTKN may inhibit AEG, thereby curbing the proliferation of gastric cancer cells." (PMID 39906672, 2024). "However, the specific mechanisms by which RTKN regulates AEG are not fully understood, necessitating further research to elucidate its role in the development of gastric cancer." (PMID 39906672, 2024).
breast carcinoma (5 papers, 2010 to 2023). "In breast cancer, loss of miR-145 resulted in an elevation of rhotekin (RTKN), a scaffolding protein for Rho-GTP that is involved in cell proliferation." (PMID 20515486, 2010). "Supporting this idea, RTKN has been already proven to be targeted by miR-145 in breast cancer, FSNC1 in colon cancer and melanoma, and GOLM1 in prostate cancer." (PMID 32403239, 2020). "Over-expressing miR-145 in breast cancer cells suppresses the cell growth and induces apoptosis through downregulating ERα and Rhotekin expression." (PMID 24923427, 2014). "miR-145 inhibits breast cancer cell growth by targeting RTKN." (PMID 37373169, 2023).
colon cancer (5 papers, 2020 to 2023). "A colon cancer cell analysis revealed that the long non-coding RNA HULC interacts with miR-613 to regulate colon cancer growth and metastasis by targeting RTKN." (PMID 37373169, 2023). "LncRNA HULC accelerates the proliferation of colon cancer cells by miR-613/RTKN 28, while lncRNA Xist, as the endogenous sponge of miR-137, upregulates Rac1, which is the target gene of miR-137 and promotes the proliferation of glioma cells." (PMID 34257656, 2021). "Downregulation of HULC attenuates the metastasis of colon cancer cells by interacting with miR-613 and modulating RTKN." (PMID 33246471, 2020). "Downregulation of HULC impairs colon cancer cell proliferation in vitro and retards tumor growth in mice by regulation of miR-613/rhotekin (RTKN)." (PMID 33246471, 2020). "LncRNA HULC knockdown inhibits cell migration and invasion by modulating miR-613/RTKN expression in colon cancer cells." (PMID 33246471, 2020).
hepatocellular carcinoma (3 papers, 2018 to 2026). A malignant tumor that arises from hepatocytes. "Furthermore, the pathophysiological role of Rhotekin was investigated in hepatocellular carcinoma (HCC), the most common adult liver cancer, which explains approximately 90% of all cases of primary liver cancer annually." (PMID 30037057, 2018).
bladder cancer (2 papers, 2018 to 2020). "Studies have shown that RTKN is highly expressed in bladder cancer, and some experiments have shown that some miRNA can inhibit tumor growth by targeting RTKN." (PMID 32843852, 2020). "In human bladder carcinoma, mRNA levels of Rhotekin were significantly higher in surgically resected specimens than in tumor-free bladder tissues, suggesting that Rhotekin takes part in bladder carcinogenesis and the carcinoma progression." (PMID 30037057, 2018). "Among them, only C16orf74 and RTKN were previously reported to be associated with bladder cancer, while other genes were not reported and are worthy of future research for bladder cancer." (PMID 32843852, 2020).
lung carcinoma (2 papers, 2022 to 2023). "Studies on lung cancer cells have shown that RTKN inhibition exerts antitumor effects and that RTKN is associated with a sensitivity to HSP90 inhibitors." (PMID 37373169, 2023). "An increasing number of studies have found that RTKN plays an important role in the development of many human cancers, including breast, colon, gastric, and lung cancers." (PMID 37373169, 2023).
pemphigus (1 paper, 2012). Pemphigus is a group of rare autoimmune diseases that cause blistering of the skin and mucous membranes (mouth, nose, throat, eyes, and genitals).This conditioncan occur at any age, but often strikes people in middle or older age. "Since inhibition of RhoA has been shown to be induced by pemphigus autoantibodies that disrupt Dsg3 and Dsg1 adhesion we also performed RhoA pull down in parallel using the GST fused Rhotekin-PBD." (PMID 22796473, 2012).
tumor (13 papers, 2018 to 2026). "Collectively, these findings suggest that RTKN overexpression modulates the tumor-inhibitory effects of PSMD1 knockdown in HCC." (PMID 41535254, 2026). "In contrast, the expressions of GOLM1 and RTKN in the tumor tissues (8.549 ± 1.034 and 1.782 ± 0.228, respectively) were significantly higher than those in the adjacent normal tissues (1.766 ± 0.113 and 1.247 ± 0.128, respectively) (p < 0.001 and p = 0.018)." (PMID 37373169, 2023). "Rhotekin (RTKN), a tumor-promoting protein, was also confirmed as a direct target of miR-152 to reduce tumor development." (PMID 34069740, 2021). "In this context, recent studies have reported that micro RNAs (miRNAs), miRNA-152 and let-7a are likely to inhibit tumor cell growth through the down-regulation of Rhotekin expression." (PMID 30037057, 2018). "Moreover, Kaplan-Meier survival analysis of the TCGA dataset revealed that elevated RTKN expression was associated with poorer overall survival (OS) in HCC patients, consistent with its elevated expression levels in tumor tissues." (PMID 41535254, 2026). "MiR-152 also directly targets rhotekin, a tumor-promoting protein, to reduce tumor development." (PMID 36016398, 2022). "The downstream proteins of Rho GTPase related to tumor regulation mainly include ROCK, PAK, Rhotekin (RTKN), etc." (PMID 38155217, 2023). "To evaluate whether AKT contributes to tumor progression through the PI3K/AKT pathway, we treated RTKN-overexpressing cells with LY294002, a PI3K inhibitor." (PMID 41535254, 2026). "Finally, hsa-miR-145 acts as a tumor suppressor through the inhibition of different proteins like ERBB3 and RTKN." (PMID 32635415, 2020).
cancer (6 papers, 2017 to 2026). A tumor composed of atypical neoplastic, often pleomorphic cells that invade other tissues. "In this review, we summarize known features of Rhotekin and its binding partners in neuronal tissues and cancer cells." (PMID 30037057, 2018). "The miR-145 is able to suppress cancer proliferation, invasion and metastases through suppression of mucin-1, RTKN, c-Myc, and EGFR." (PMID 28456786, 2017). "The involvement of RTKN in cancers has recently been investigated." (PMID 41535254, 2026). "High expression of RTKN has been reported in several cancers." (PMID 41535254, 2026). "Since Rhotekin is abundantly expressed in brain tissues and in several kinds of cancer cells, the investigation of Rhotekin function may also contribute to the understanding of the pathophysiology of neurodevelopmental disorder and cancer." (PMID 30037057, 2018). "Enhanced expression of Rhotekin was also detected in other cancer cells." (PMID 30037057, 2018). "Consequently, S100A4 and Rhotekin are most likely to contribute to the conferring of invasive phenotypes of cancer cells." (PMID 30037057, 2018). "Taken together, Rhotekin-mediated signaling pathways may be a novel therapeutic target for cancer." (PMID 30037057, 2018). "Indeed, there are several reports describing the abnormal expression of Rhotekin in cancer cells." (PMID 30037057, 2018).
RTKN also shares sentences with these, for which no sentence is quoted: colitis (1 paper); coronary heart disease (1); glioma (1); infection (1); liver cancer (1); melanoma (1); myopia (1); neurodevelopmental disorder (1); prostate carcinoma (1); psychiatric diseases (1); Thymic Epithelial Tumors (1).